ID2B (inhibitor of DNA binding 2B (pseudogene))
Gene: Processed pseudogene on chromosome 3 (62,124,204 to 62,124,608, reverse strand). Ensembl gene ENSG00000237456.
Diseases named in the same sentence as ID2B in open-access papers:
ID2B is named in the same sentence as 1 disease in open-access papers, as found by Europe PMC text mining. Sharing a sentence is not in itself a finding about the gene and the disease. The quoted sentences say what the papers report.
cardiomyopathy (1 paper, 2025). A disease of the heart muscle or myocardium proper. "Upon dissecting hearts from these id2b-/- zebrafish, a prominent enlargement in the atrium with a smaller ventricle was detected (bottom), which has been characterized as cardiomyopathy in zebrafish." (PMID 40704996, 2025). "Compared to id2b+/+ controls, id2b-/- embryos exhibited markedly decreased calcium transient amplitude, consistent with compromised calcium handling observed in other zebrafish cardiomyopathy models." (PMID 40704996, 2025).